C5AR1 (complement C5a receptor 1)
Diseases named in the same sentence as C5AR1 in open-access papers (continued):
Sharing a sentence is not in itself a finding about the gene and the disease.
renal fibrosis (5 papers, 2016 to 2025). A final common manifestation of a wide variety of chronic kidney diseases characterized by glomerulosclerosis and tubulointerstitial fibrosis. "Taken together, these findings indicate that C5aR1 deficiency protects mice from renal fibrosis and parenchymal loss following renal infection." (PMID 27370410, 2016). "Recently, the role of PCs in producing Complement Component 5a Receptor 1 (C5aR1) in renal fibrosis was shown." (PMID 36831136, 2023). "To further investigate the impact of C5aR1 on the development of renal fibrosis, we assessed the extent of collagen deposition and extracellular matrix production in kidneys from WT and C5aR1-/- mice following renal infection." (PMID 27370410, 2016). "In total, these data suggest that the secretion of complement components (C1q and C5a/C5aR1) by PCs contributes to the development of renal fibrosis, thus the inhibition of complement activation represents a potential therapeutic target in treatment of kidney fibrosis and chronic kidney disease." (PMID 36831136, 2023). "Here we tested whether the development of chronic inflammation and renal fibrosis is dependent on C5aR1 in a murine model of chronic pyelonephritis." (PMID 27370410, 2016). "To further investigate whether the major effects of C5aR1 on chronic inflammation and renal fibrosis are dependent on the initial impact of C5aR1 or the subsequent responses, we performed an additional set of in vivo experiments." (PMID 27370410, 2016). "In addition, the expression of genes associated with complement and coagulation activation, such as F3, Fga, Pai1, C3, and C5ar1, was also elevated in the two different renal fibrosis models, indicating the upregulation of local renal coagulation and complement cascades in the pathogenesis of CKD." (PMID 41324413, 2025). "Additionally, our study found that C5aR1 has a big impact on the development of renal fibrosis." (PMID 27370410, 2016).
acute respiratory distress syndrome (4 papers, 2020 to 2024). Progressive and life-threatening pulmonary distress in the absence of an underlying pulmonary condition, usually following major trauma or surgery. "Carvelli and colleagues demonstrated the role of the C5a-C5AR1 axis in the pathophysiology of acute respiratory distress syndrome (ARDS) in severe COVID-19." (PMID 36232655, 2022).
airway hyperresponsiveness (4 papers, 2013 to 2018). "Further, C5 or C5aR1 targeting is associated with increased airway hyperresponsiveness." (PMID 28231307, 2017).
brain injury (4 papers, 2019 to 2025). Acute and chronic (see also brain INJURIES, CHRONIC) injuries to the brain, including the cerebral hemispheres, CEREBELLUM, and brain STEM. "That is, TLR4 and C5aR1 represent an alternative upstream regulator in activating NF-κB by inhibiting cAMP/PKA signals and participate in TNF-α, IL-1β, and IL-6 production in MCAO/R-induced brain injury." (PMID 33633530, 2021).
Cerebral ischemia (4 papers, 2014 to 2024). Restriction of arterial blood supply to the brain associated with insufficient oxygenation to support the metabolic requirements of the tissue. "Therapeutic hypothermia (HT) combined with the inhibition of the expression of C5aR1 could reduce brain infarct volume within 3 days of brain ischemia." (PMID 31011487, 2019). "TLR4 and C5AR1 promote apoptosis and inflammation by activating the cAMP/PKA/I- κB/NF- κB signaling pathway during brain ischemia-reperfusion." (PMID 38650649, 2024).
fungal infection (4 papers, 2012 to 2025). "In murine models of systemic fungal infection, the C5a-C5aR1 axis is essential for controlling Candida species, as evidenced by the significantly increased mortality and markedly elevated fungal burden observed in C5aR1 knockout mice resulting from infection." (PMID 41584453, 2025). "C5aR1 ablation has confirmed that the C5a/C5aR1 axis in renal macrophages promotes ERK- and AKT-dependent survival during fungal infection." (PMID 41031895, 2025).
ischemia (4 papers, 2019 to 2021). A hypoperfusion of the BLOOD through an organ or tissue caused by a PATHOLOGIC CONSTRICTION or obstruction of its BLOOD VESSELS, or an absence of BLOOD CIRCULATION. "Comparing ischemic hindlimb muscles from platelet-specific C5aR1-deficient mice with Pf4-cre−C5ar1fl/fl control mice at day 14 after induction of ischemia, we observed increased pericyte density and enhanced pericyte coverage in platelet-specific C5aR1-deficient mice." (PMID 34099640, 2021). "We observed differences in hindlimb revascularization between the assessed genotypes (WT versus C5ar1−/− or Pf4-cre+/−C5ar1fl/fl) after the onset of ischemia." (PMID 34099640, 2021). "We also considered the possibility that platelet C5aR1 impacts on the formation of pre-existent collateral vessels, which are known to be important for the initial phase of ischemia-induced revascularization." (PMID 34099640, 2021). "Next, we explored the functional role of C5aR1 in vessel formation in vivo by assessing murine embryonic angiogenesis and hindlimb ischemia-induced revascularization." (PMID 34099640, 2021). "More specifically, we demonstrate that platelet C5aR1 inhibits endothelial functions in vitro and decreases growth factor-induced angiogenesis and ischemia-induced revascularization in vivo." (PMID 34099640, 2021). "Here we observed a specific inhibitory effect of platelet C5aR1 in ischemia-induced revascularization." (PMID 34099640, 2021). "Vessel density of hindlimb muscles from C5ar1−/− mice was significantly higher as compared with that of WT controls after the induction of hindlimb ischemia." (PMID 34099640, 2021). "In a mouse model of permanent focal ischemia, C5aR1 mRNA expression was increased after 3 hours up to 21 days post-ischemia." (PMID 31011487, 2019). "The protective effect of inhibiting C5aR1 during ischemic pathological conditions was demonstrated in a rat model of acute limb ischemia-reperfusion, rodent intestinal ischemia-reperfusion, and rat hepatic ischemia-reperfusion." (PMID 31011487, 2019). "Interestingly, we detected significantly lower levels of CXCL4 in homogenized hindlimb muscles of C5ar1−/− mice subjected to hindlimb ischemia than in those of WT littermate controls." (PMID 34099640, 2021).
leukemia (4 papers, 2009 to 2025). A malignant (clonal) hematologic disorder, involving hematopoietic stem cells and characterized by the presence of primitive or atypical myeloid or lymphoid cells in the bone marrow and the blood. "Our previous study demonstrated that LukS-PV can induce differentiation and apoptosis in leukemia cells by targeting C5aR1, displaying antileukemia activity in vitro and in vivo, without noticeable side effects in mice." (PMID 39736396, 2025).
liver fibrosis (4 papers, 2017 to 2023). "C5 or C5aR1 deficiency diminished hepatic fibrosis, inflammatory response, and lipid accumulation in NASH." (PMID 37227481, 2023). "We speculate that C5 deficiency attenuates liver fibrosis through the anaphylatoxin receptor C5aR1 in NASH mice." (PMID 37227481, 2023). "Further interaction analysis showed that neutrophils and other immune cells had extensive ‘RPS19‐C5AR1’ communications, and previous studies showed that C5AR1 is closely related to liver fibrosis." (PMID 36333281, 2022). "Moreover, we found that administration of PMX-53, the C5aR1 antagonist, significantly reduced liver fibrosis, inflammation and steatosis in mice." (PMID 37227481, 2023). "A previous study showed that C5aR1 plays a critical role in the induction of liver fibrosis." (PMID 37227481, 2023). "In conclusion, our data identified lnc-HSER as a novel regulator of C5AR1-Hippo-YAP and Notch pathways in liver fibrosis, suggesting that lnc-HSER might be a novel biomarker and a candidate of anti-fibrotic targets." (PMID 31695787, 2019).
lung disease (4 papers, 2020 to 2026). "Due to both the detection of C5a in the bronchoalveolar lavage fluid of COVID-19 patients with ARDS and pulmonary infiltration of macrophages largely expressing C5aR1, an association between C5a and lung disease caused by SARS-CoV-2 infection has been proposed." (PMID 33669011, 2021). "The NLRP3 MFI on CD3 positive of early-stage NSCLC patients showed higher expression than non-malignant pulmonary disease whereas C5AR1 and CLEC4A expression levels were not different." (PMID 36323738, 2022). "The median ratios of C5AR1, CLEC4A and NLRP3 expression in CD3+ of non-malignant pulmonary diseases were 0.01 [range 0–0.02, p = 0.12], 0.02 [range 0.01–0.08, p = 0.42] and 0.13 [range 0.07–0.22, p = 0.14], respectively." (PMID 36323738, 2022).
non-small cell lung carcinoma (4 papers, 2021 to 2025). A group of at least three distinct histological types of lung cancer, including non-small cell squamous cell carcinoma, adenocarcinoma, and large cell carcinoma. "Both these data and our present findings support C5AR1 as a primary mechanism in non-small cell lung cancer." (PMID 36323738, 2022). "In non-small-cell lung cancer (NSCLC) for example, higher C5aR1 levels in the primary tumor predict bone metastasis and result in decreased overall survival and relapse free survival." (PMID 36003145, 2022).
peritonitis (4 papers, 2008 to 2024). Inflammation of the peritoneum (tissue that lines the abdominal wall and covers most of the organs in the abdomen). "Thus, in the inflammatory state of peritonitis, C5aR1 and C5aR2 signals might cooperate in modulating macrophage inflammatory responses." (PMID 39021433, 2024).
renal cell carcinoma (4 papers, 2020 to 2025). "In a mouse renal cell carcinoma (RCC) model, genetic deficiency of C3aR or pharmacological inhibition of either C3aR or C5aR1 resulted in reduced tumor growth." (PMID 35860237, 2022). "The most recent study, showing the striking impact of complement genes on outcomes in renal cell carcinoma (RCC), found that C3aR-deficiency or blockade and C5aR1 blockade were all associated with reduced vascular density of tumors in a mouse model of RCC." (PMID 33488603, 2020).
acute pyelonephritis (3 papers, 2017 to 2024). "In the context of infectious diseases, our recent study in a murine model of acute pyelonephritis has shown that the C5a/C5aR1 axis plays a pathogenic role in kidney infection." (PMID 35433513, 2022). "C5aR1 plays a pathogenic role in acute pyelonephritis and facilitates bacterial colonization of epithelium." (PMID 29263309, 2017). "Similarly, we have also proved the pro-inflammatory and pathogenic role of C5aR1 and C5aR2 in acute pyelonephritis in mice." (PMID 39021433, 2024).
anaphylaxis (3 papers, 2016 to 2024). An acute hypersensitivity reaction that occurs from exposure to an allergen. "Thus, we identify C5aR1 as a new potential target for the prevention and treatment of anaphylaxis and CIPN in patients receiving paclitaxel." (PMID 35614037, 2022).
breast tumors (3 papers, 2021 to 2025). "The receptor for complement component C5a, C5aR1, is reportedly highly expressed in a variety of cancers, including tumors of the breast, colon, and gastric, with high expression of C5aR1 generally associated with poor prognosis." (PMID 39736396, 2025). "To explore the clinical relevance of C5aR1+ neutrophils in BC, we generated a gene signature (CD66b, CD15, and C5aR1) to examine the abundance of C5RN in primary breast tumors." (PMID 34312368, 2021). "In addition, atovaquone treatment suppressed the expression of C5aR1 in human breast tumors HCC1806 as shown by IHC analysis." (PMID 34068008, 2021).
bullous pemphigoid (3 papers, 2018 to 2024). Bullous pemphigoid (BP) is the most common form of autoimmune bullous dermatosis. "We assessed the efficacy and safety of avdoralimab, a specific anti-C5aR1 mAb, for treating bullous pemphigoid." (PMID 39310808, 2024). "While C5aR1 showed a proinflammatory effect in a mouse model of bullous pemphigoid and epidermolysis bullosa acquisita, C5aR2 demonstrated an anti-inflammatory effect in the same mouse model of bullous pemphigoid." (PMID 30524436, 2018). "Rationale: Experimental data support the role for C5a–C5aR1 axis activation in bullous pemphigoid." (PMID 39310808, 2024).
cerebral malaria (3 papers, 2017 to 2024). A sequestration of Plasmodium falciparum in the brain, which can cause coma and/or seizures. "Both C5aR1 and C5aR2 (C5L2) receptors are involved in the physio-pathological functions of various ocular diseases, such as retinitis pigmentosa (C5L2), human and experimental cerebral malaria (only C5aR1), or choroidal neovascularization (in mice)." (PMID 39195219, 2024).
clear cell renal carcinoma (3 papers, 2016 to 2021). A malignant epithelial neoplasm of the kidney characterized by the presence of lipid-containing clear cells within a vascular network. "Elevation of C5a or C5aR1 levels has been observed in solid tumors including lung, gastric, ovarian, breast, urothelial, and clear cell renal cancers." (PMID 31001273, 2019).
endotoxemia (3 papers, 2012 to 2022). "Thus, this 43% reduction in plasma IL-1β detected during LPS-induced endotoxemia—attributable to a loss of C5aR1 signaling—strongly suggested that C5a engages C5aR1 in vivo to amplify TLR4-mediated IL-1β production in the endotoxemia model." (PMID 27382187, 2016). "The results of our study suggest that C5a-C5aR1 interactions are critical for enhancing the innate IL-1β response during LPS-induced endotoxemia." (PMID 27382187, 2016).
epilepsy (3 papers, 2020 to 2025). A brain disorder characterized by episodes of abnormally increased neuronal discharge resulting in transient episodes of sensory or motor neurological dysfunction, or psychic dysfunction. "C5aR1 is primarily expressed on myeloid cells, including microglia, and C5aR1 signaling is involved in brain dysfunctions associated with neuroinflammation, such as epilepsy and neurodegenerative disorders." (PMID 33613523, 2020). "Overall, the epilepsy literature supports a node-based model in which aberrant C1q/C3 activity remodels synapses and glia, C5aR1 signaling amplifies inflammation and excitability, and terminal-pathway overactivity risks direct cytotoxicity, each providing a mechanistic foothold for therapy." (PMID 41458814, 2025).
fibrosis (3 papers, 2018 to 2025). the formation of excess fibrous connective tissue in an organ or tissue in a reparative or reactive process. "The inhibition of the C5a-C5aR1 axis significantly reduced renal injury and tubulointerstitial fibrosis, suggesting a pathogenic role for C5aR1 in the progression of fibrosis after renal IRI." (PMID 39857400, 2025). "Furthermore, C5aR1‐mediated local inflammatory response contributes to tubulointerstitial fibrosis progression after renal ischemia reperfusion injury." (PMID 41324413, 2025).
food allergy (3 papers, 2020 to 2025). Gastrointestinal disturbances, skin eruptions, or shock due to allergic reactions to allergens in food. "Furthermore, C5aR1 was shown to modulate intestinal tight junctions in an IgE-mediated food allergy by indirectly modulating the histamine-mediated opening of endothelial tight junctions." (PMID 37726739, 2023). "Furthermore, the use of C3ar1-/- and C5ar1-/- MCs in passive cutaneous anaphylaxis (PCA) mouse models and C5ar1-/- mice in oral food allergy models has demonstrated the contribution of anaphylatoxin signaling pathways in IgE-induced MC activation." (PMID 33597949, 2020).
glomerular diseases (3 papers, 2019 to 2025). "The effect of the C5a and C5aR1 targeting compounds Vilobelimab (IFX-1) and Avacopan (CCX168) demonstrate the relevance of the inflammatory axis of complement in glomerular diseases." (PMID 34613485, 2021).
gout (3 papers, 2021 to 2025). A condition characterized by painful swelling of the joints, which is caused by deposition of urate crystals. "These research findings indicate that CPI2 can ameliorate MSU-induced gouty arthritis by regulating the C5a-C5aR1 axis." (PMID 40584622, 2025). "The knockout of the C5aR1 gene was beneficial for inhibiting the inflammation of MSU-induced gouty arthritis." (PMID 40584622, 2025). "In this study, we investigated the protective effect of CPI2 against MSU-induced gouty arthritis using wild-type (WT) and C5aR1 knockout (C5aR1−/−) mice and preliminarily evaluated the underlying mechanisms." (PMID 40584622, 2025). "Our study reveals that 24 h after MSU injection in mice, the serum C5a level in mice with acute gouty arthritis increases significantly, and concurrently, the expression of C5aR1 protein is upregulated." (PMID 40584622, 2025). "When C5aR1 is knocked out, the symptoms of mice with acute gouty arthritis are significantly alleviated, and the inflammatory and oxidative stress indexes are obviously improved, which indicates that the C5a - C5aR1 axis is involved in the progression of acute gouty arthritis." (PMID 40584622, 2025). "C5aR1 is involved in the progression of acute gouty arthritis induced by MSU." (PMID 40584622, 2025). "C5aR1 is involved in the oxidative stress process of acute gouty arthritis induced by MSU." (PMID 40584622, 2025). "C5aR1 is involved in the immunoregulation and inflammation of acute gouty arthritis induced by MSU." (PMID 40584622, 2025). "Knocking out or blocking C5aR1 helps alleviate the inflammation of acute gouty arthritis." (PMID 40584622, 2025). "C5aR1 is involved in the inflammatory progression of acute gouty arthritis induced by MSU." (PMID 40584622, 2025). "Furthermore, we explored the effect of C5aR1 on MSU-induced gouty arthritis and verified whether CPI2 alleviates gouty arthritis through C5aR1." (PMID 40584622, 2025). "Compared with colchicine, CPI2 is superior in reducing the swelling of the footpad in acute gouty arthritis induced by MSU, increasing the activity of GSH-Px, and decreasing the levels of CTSS and C5aR1." (PMID 40584622, 2025). "An enzyme activity inhibition assay was conducted to detect the inhibitory effect of CPI2 on cathepsin S. In an attempt to mimic human gouty arthritis, suspensions of monosodium urate (MSU) crystals were injected into the right foot pads of C57BL/6 wild-type (WT) mice and C5aR1−/− mice." (PMID 40584622, 2025). "CPI2 may alleviate gouty arthritis by reducing the level of CTSS and regulating the C5a-C5aR1 axis." (PMID 40584622, 2025).
liver cancer (3 papers, 2019 to 2025). An epithelial or non-epithelial malignant neoplasm that arises from the liver. "Taken together, these results indicated that HDAC7 as a potential prognostic marker for liver cancer, and LukS-PV can downregulate the high expression of HDAC7 by targeting C5aR1 in HCC cells." (PMID 39736396, 2025). "Next, we investigated the relationship between the expression levels of C5aR1, HDAC7, and CTNNB1 in liver cancer cases from TCGA database." (PMID 39736396, 2025).
mastitis (3 papers, 2009 to 2020). Inflammation of breast tissue during lactation or postpartum due to an obstructed duct or infection. "It is worth acknowledging that a less conservative estimate (uncorrected p ≤ 0.05) indicated upregulation of one other candidate gene (C5AR1) at the onset of mastitis, and ongoing upregulation of LCN2 and PGLYRP1 at sampling points 2 and 3, respectively." (PMID 33195534, 2020). "Although C5AR1 was not identified as a candidate gene within our previous postpartum study, perhaps due to lactation stage effects, it was selected for this study due to its integrated resistance and tolerance mechanisms and association with mastitis traits in expression studies." (PMID 33195534, 2020). "Of the four genes (C5AR1, CATHL6, LCN2, and PGLYRP1) with evidence of upregulation in cows with mastitis, three of those genes (CATHL6, LCN2, and PGLYRP1) were investigated due to their previously identified association with postpartum disease." (PMID 33195534, 2020).